STRN3 (striatin 3)
Diseases named in the same sentence as STRN3 in open-access papers:
STRN3 is named in the same sentence as 21 diseases in open-access papers, as found by Europe PMC text mining. Sharing a sentence is not in itself a finding about the gene and the disease. The quoted sentences say what the papers report.
gastric cancer (6 papers, 2022 to 2025). A primary or metastatic malignant neoplasm involving the stomach. "In the context of the Hippo pathway in gastric cancer, Striatin 3 facilitates MST1/2 dephosphorylation through protein phosphatase 2A (PP2A), activating YAP and driving gastric cancer progression." (PMID 40066231, 2025). "According to Tang, strikingly increased STRN3 protein expression was observed in the gastric cancer cell line HGC27 compared with the normal gastric epithelium cell GES-1." (PMID 38201504, 2023). "In support of these observations, Striatin 3 has been found to be overexpressed in human gastric cancers, leading to inactivation of the Hippo pathway and hyperactivation of the proto-oncogene YAP1." (PMID 36328247, 2022). "Striatin 3 upregulation resulted in hyperactivation of YAP1, leading to loss of Hippo tumor-suppressive functions, which ultimately correlated with poor prognosis in a cohort gastric cancer patients." (PMID 36328247, 2022). "In this regard, we recently discovered an upregulation of STRN3 in gastric cancer (GC) cells, with STRN3 recruiting MST1/2 to the PP2A core enzyme to dephosphorylate MST1/2, a process that turns off the tumor-suppressive activity of Hippo signaling." (PMID 35290241, 2022). "A novel selective inhibitor of the PP2A-STRN3 complex, STRN3-derived Hippo-activating peptide (SHAP), exerts antitumor effects by interrupting MST1/2-mediated YAP activation in gastric cancers." (PMID 39776803, 2025). "Additionally, the STRN3-derived Hippo-activating peptide (SHAP), designed to target the PP2Aa–STRN3 interaction region, has demonstrated the restoration of Hippo activity and reduced gastric cancer tumour size in xenograft mouse models." (PMID 38201504, 2023).
medulloblastoma (4 papers, 2022 to 2023). A malignant, invasive embryonal neoplasm arising from the cerebellum. "Co-depletion of MAP4K4 and striatin 3 (STRN3) caused a near-complete eradication of medulloblastoma and completely abrogated cell dissemination in vitro." (PMID 37190200, 2023). "However, depletion of either STRN3 or MAP4K4 in medulloblastoma cells reduces invasion, and loss of both proteins abrogates tumor cell growth in the cerebellar tissue." (PMID 35941177, 2022). "Accordingly, STRN3/4 depletion could reduce the invasive capacity of medulloblastoma cells." (PMID 37223681, 2023). "The cooperation of MAP4K4 and STRN3 in the STRIPAK complex promotes a pro-migratory and invasive phenotype in medulloblastoma cells through the activation of downstream effector PKCθ." (PMID 36568222, 2022). "In an in vitro model of medulloblastoma, MAP4K4 interacted with STRN3/4 and stimulated cell growth." (PMID 37223681, 2023). "Thus, STRN3 is a master regulator of MAP4K4 function, and disruption of its cooperation with MAP4K4 reactivates Hippo signaling and represses tissue invasion in medulloblastoma." (PMID 35941177, 2022).
breast carcinoma (3 papers, 2023 to 2025). "Clinically, breast cancer patients who expressed higher level of STRN3, CCM3, PPP2CA, and PPP2CB were shown to be more sensitive to chemotherapies." (PMID 38201504, 2023). "In breast cancer, STRN3 was found to have increased expression in breast cancer tumour tissues compared with adjacent normal tissues, at both the transcript and protein levels." (PMID 38201504, 2023). "However, the involvement of STRN3 in breast cancer patients’ drug responses was also reported to be hormone-receptor-status dependent." (PMID 38201504, 2023). "Additionally, STRN3 has also been shown to be significantly upregulated in female breast cancer." (PMID 40124499, 2025). "For example, a recent study found that STRN3 cooperates with MAP4K4 to promote growth and tissue invasion in breast cancer cells." (PMID 39148682, 2024).
heart failure (3 papers, 2019 to 2024). Inability of the heart to pump blood at an adequate rate to meet tissue metabolic requirements. "These showed a significant increase in only STRN3 mRNA expression in heart failure samples, although protein expression of all striatins was significantly increased in failing hearts." (PMID 38718356, 2024). "Longer term studies would also help to determine if STRN3 plays an important role in developing heart failure, as suggested by the minor abnormalities in longitudinal strain we detected in STRN3+/− mice treated with AngII over 7 d." (PMID 38718356, 2024). "This study only considers the role of STRN and STRN3 in the early stages of cardiac remodelling induced by AngII, not the later stages associated with heart failure and decreased ejection fraction." (PMID 38718356, 2024). "In doxorubicin-induced heart failure, the RBP Qki5 interacts with circRNAs Ttn, Fhod3, and Strn3 to improve cardiac function." (PMID 30736838, 2019). "Thus, although STRN and STRN3 have a similar profile overall with up-regulation in disease, STRN4 may have more specific and selective roles in different forms of heart failure." (PMID 38718356, 2024).
brain tumor (1 paper, 2022). "The interaction of the STRIPAK complex with MAP4K4 confirms previous findings describing a direct interaction of STRIPAK with MST1/2, MST3/4, and MAP4Ks19,25,33,34 in a brain tumor, where MAP4K4 and STRN3/4 are highly expressed." (PMID 35941177, 2022).
cardiac hypertrophy (1 paper, 2024). "Overall, the data indicate that reduction of STRN3 does not substantially affect cardiac hypertrophy induced by AngII, at least over the short term." (PMID 38718356, 2024).
Hypertension (1 paper, 2024). The presence of chronic increased pressure in the systemic arterial system. "SNPs in a second isoform, striatin 3 (STRN3, also known as SG2NA) are also linked to hypertension." (PMID 38718356, 2024). "However, STRN3 may play an important role in later phases of hypertension-induced cardiac dysfunction and/or in other cardiac pathologies (e.g., myocardial infarction that results in acute injury)." (PMID 38718356, 2024).
liver cancer (1 paper, 2024). An epithelial or non-epithelial malignant neoplasm that arises from the liver. "Through experiments, we found that the mRNA expression of STRN3 in the adjacent tissues of these 24 liver cancer patients was significantly lower than its expression in the tumours." (PMID 38429901, 2024).
lung adenocarcinoma (1 paper, 2025). A carcinoma that arises from the lung and is characterized by the presence of malignant glandular epithelial cells. "In the current study, we validated the anti‐tumor properties of STRN3 in lung adenocarcinoma through a series of experiments on cell functions." (PMID 40068093, 2025).
lung carcinoma (1 paper, 2025). "The intense interaction between endogenous TRAF3IP3 and STRN3 in lung cancer cells was validated by co‐immunoprecipitation (Co‐IP) using A549, PC9, and H1299 cell lysates." (PMID 40068093, 2025). "By western blotting analysis, we found that STRN3 presented lower expression in lung cancer cells (A549, PC9, and H1299) compared with normal bronchial epithelial cells (BEAS‐2B), with the lowest expression in A549 cells." (PMID 40068093, 2025). "Although previous studies have shown that STRN3 is essential for ER stress, it is unclear whether it is involved in cellular physiological processes like TRAF3IP3 in lung cancer, such as regulating apoptosis and prolonged ER stress." (PMID 40068093, 2025).
nasopharyngeal carcinoma (1 paper, 2024). A carcinoma arising from the nasopharyngeal epithelium. "This research establishes that AC008083.2 functions as a competitive regulatory mediator for miR-142-3p, thereby competitively regulating the STRN3 expression associated with Nasopharyngeal Carcinoma (NPC)." (PMID 39148682, 2024).
oesophageal cancer (1 paper, 2023). "An upstream oncogenic regulator of STRN3, miR-885-5p, was recently identified and found to facilitate malignant behaviour in oesophageal cancer cells via regulating the STRN3-mediated Hippo cascade." (PMID 38201504, 2023).
uterine sarcoma (1 paper, 2024). "In this report, we present the first case of STRN3::NTRK3 fused uterine sarcoma metastatic to the spleen, properly classified after the excision of the secondary distant localization." (PMID 39582973, 2024).
tumor (12 papers, 2022 to 2025). "On the other hand, we observed the expression of STRN3 in tumour tissues of White patients is higher than that of African American patients, and it also had an association with tumour status (p = 0.039)." (PMID 38429901, 2024). "This is consistent with our previous finding from TCGA database analysis, which showed that high expression of STRN3 in tumour tissues was associated with poor prognosis in HCC patients." (PMID 38429901, 2024). "The combined depletion of MAP4K4 and STRN3 in DAOY cells caused a dramatic reduction of tumor area, both under basal condition and under EGF stimulation." (PMID 35941177, 2022). "Remarkably, however, co-depletion of MAP4K4 and STRN3 caused a near-complete eradication of the tumor cells and completely abrogated cell dissemination in vitro." (PMID 35941177, 2022). "Depletion of STRN3 caused compaction of the tumor cell spheroids and prevented tissue invasion also under EGF-stimulation." (PMID 35941177, 2022). "We found that STRN3 depletion caused a significant reduction of tumor area." (PMID 35941177, 2022). "Additionally, we used bioinformatics to analyse the biological function of STRN3 protein and found that it is mainly associated with transcriptional abnormalities in tumours, and the results also indicated that there was a high correlation between STRN3 and the Hippo pathway in HCC." (PMID 38429901, 2024). "MAP4K4 and STRN3 cooperate to promote tissue invasion and regulate tumor growth by modulating Hippo signaling." (PMID 41034525, 2025). "Analysis of TCGA and GEO databases, along with the immunohistochemical staining analysis revealed that compared to normal liver tissue, STRN3 was significantly upregulated in tumour tissue." (PMID 38429901, 2024). "Gender had a slight effect on STRN3 expression, with females showing a higher level of STRN3 enrichment in tumour tissue than males (p = 0.003)." (PMID 38429901, 2024). "Our previous study identified STRN3 as a key regulatory subunit recruiting MST1/2 kinases to the PP2A core enzyme and thereby causing loss of Hippo tumor suppressor signaling in GC." (PMID 38657866, 2024). "Immunohistochemistry was used to assess the expression of STRN3 in patients' tumour and adjacent non‐cancerous tissues." (PMID 38429901, 2024). "Second, we have not conducted animal experiments to demonstrate the effect of STRN3 on tumour development in vivo." (PMID 38429901, 2024). "In particular, the STK3, C9orf78 and STRN3 genes were the direct targets of both miR-34c and miR-449a, and their regulation are predictive of tumour progression." (PMID 38215077, 2024). "The results visually demonstrated that the expression of STRN3 in the adjacent tissues was significantly weaker than in the tumours." (PMID 38429901, 2024). "Both STK3 and STRN3 are two important components of the Hippo pathway, which is a key tumour suppressor pathway involved in tissue regeneration, angiogenesis, tumour suppression and metastasis, immune response, and drug resistance." (PMID 38215077, 2024). "We collected a small cohort of HCC patients and conducted tests on the mRNA and protein expression of STRN3 in tumour and adjacent non‐cancerous tissues." (PMID 38429901, 2024). "A recent study, examining the expression profile of STRN3, confirmed the existence of two larger isoforms (78 and 87 kDas) in human normal mammary tissue and low-staged tumour tissues." (PMID 38201504, 2023). "The authors sought to prevent the PP2A-Striatin 3 heterotrimer from deactivating the tumor-suppressive Hippo pathway." (PMID 36328247, 2022). "Furthermore, immunohistochemistry results from the 24 patients also indicated a significant difference in STRN3 expression between the adjacent non‐cancerous tissues and the tumours." (PMID 38429901, 2024).
tumor (continued). "Finally, we evaluated the prognosis of the 24 patients using Kaplan–Meier analysis, which suggested that patients with high STRN3 expression in tumour tissues were more likely to experience recurrence after undergoing surgical treatment." (PMID 38429901, 2024). "Moreover, there was an association between STRN3 expression and Tumour stage, with patients at an advanced stage (Stage III) having a higher level of STRN3 expression (p = 0.008)." (PMID 38429901, 2024). "Our study first found that STRN3 could promote tumour growth by inhibiting the Hippo pathway." (PMID 38429901, 2024). "STRN3 facilitates the coupling of MAP4K4 to the phosphatase PP2A, thereby suppressing MAP4K4’s tumor-suppressive activity and enhancing the proinvasive behavior of MB cells." (PMID 41034525, 2025). "Our research further elucidated the important role of STRN3, as a great component of STRIPAK itself in the dephosphorylation of MST1/2 and YAP in HCC, as well as its biological impact on tumour cell proliferation and migration." (PMID 38429901, 2024). "Latter strategy was successfully used to interfere with the interaction between STRN3 and PP2A, which resulted in the reactivation of STRIPAK kinases and induction of tumor-suppressive Hippo signaling." (PMID 36568222, 2022). "The synthetised STRN3-derived Hippo-activating peptide SHAP was able to alter STRN3-PP2Aa interaction, restore MST1/2 phosphorylation capacity, and kinase the core tumour suppressor effect." (PMID 35565411, 2022). "Mechanistically, MAP4K4 interaction with STRN3 and STRN4 represses canonical MAP4K4 activity towards Hippo tumor suppressor pathway activation by bringing the kinase in proximity of PP2A." (PMID 35941177, 2022). "Recently, STRN3 has been found to be elevated in various tumours, but its expression and biological functions in HCC have not been studied." (PMID 38429901, 2024). "Inhibition of STRN3 reduced the formation of HGC27 cells colonies, and a similar inhibitory effect was additionally observed in vivo in xenograft mouse models, with reduced tumour size following STRN3 inhibition." (PMID 38201504, 2023). "On the other hand, the restored YAP/TAZ target gene expression after co-depletion of STRN3 and MAP4K4 also indicated that tumor growth suppression we observed by this treatment in the tissue cannot solely be explained by its impact on YAP/TAZ target gene expression." (PMID 35941177, 2022). "For example, PP2A phosphatase containing B55/56 regulatory subunit acts as a tumor suppressor by limiting the oncogenic activity of Myc in normal cells but may shift to play an oncogenic role due to upregulation of the STRN3 regulatory subunit in cancer cells." (PMID 38657866, 2024). "Depletion of STRN3 but not of MAP4K4 reduced tumor cell growth in the cerebellum tissue." (PMID 35941177, 2022).
cancer (11 papers, 2018 to 2025). A tumor composed of atypical neoplastic, often pleomorphic cells that invade other tissues. "STRN3 is associated with cancer development and progression." (PMID 39148682, 2024). "Previous research has shown that STRN3 functions as a scaffold protein and is up‐regulated in several types of cancer, including gastric and breast cancer." (PMID 38429901, 2024). "Studies have also demonstrated that STRN3 regulates the activation of the YAP (Yes‐associated protein) and hippo pathway, as well as being a vital upstream regulator of MAP4K4 to enhance cancer cell invasion and growth." (PMID 38429901, 2024). "Our study also identified TH as a structural analog of DSF to exert similar function in terms of targeting the PP2Aa–STRN3 interactions and restores the Hippo signaling against cancer." (PMID 38657866, 2024). "KEGG analysis revealed that the most relevant signal pathway to STRN3 is transcriptional misregulation in cancer." (PMID 38429901, 2024). "Previous study has shown that STRIPAK components FAM40A, FAM40B, and STRN3 determine the model of cancer cell migration and metastasis through regulating the contractile cytoskeleton phenotype." (PMID 36639675, 2023). "Cancer cells often feature uncontrolled proliferation, making it highly likely that STRN3 is dysregulated during the process of cancer development." (PMID 38201504, 2023). "For example, STRN3 was reported to activate the Akt signalling pathway to enhance the survival of cancer cells." (PMID 32280692, 2020). "Additionally, Western blot was used to examine the expression of STRN3 protein in 6 patients' cancer and adjacent non‐cancerous tissues." (PMID 38429901, 2024). "Many previous studies have demonstrated that MST1/2 and STRIPAK scaffolds are aberrantly expressed in different types of cancers, hence MST1/2 and STRN3 dysregulation may result in the development of various cancer." (PMID 32867200, 2020). "The increase in the stability of PARK7 by striatin 3 (STRN3) enhances the survival of cancer cells." (PMID 32357493, 2020). "Interestingly, depletion of the striatin STRN3 in human A431 carcinoma cells led to a similar phenotype to FAM40A depletion, indicating that they act on the same pathway." (PMID 30509168, 2018). "Additionally, STRN3 is involved in developing several human diseases, including cancer." (PMID 39148682, 2024). "STRIP1, STRIP2, and STRN3 have been identified as regulators of actomyosin, while MST3 and MST4, members of GCKIII kinases, regulate cancer cells migration." (PMID 38999976, 2024). "In cancer cells, STRIP1, STRIP2, and STRN3 regulate cell migration and metastasis by negatively influencing MST3 and MST4 kinases, which act through the ezrin-radixin-moesin family proteins to promote the actomyosin machinery by phosphorylating PP1 and PPP1R14A-D." (PMID 38999976, 2024). "STRN3 also increases the expression of PARK7 by inhibiting the proteasome-mediated degradation of PARK7 and subsequently activates AKT by enhancing the stability of PARK7 and increasing the formation of protein-protein complexes for protecting cancer cells from oxidative stress." (PMID 32357493, 2020).
infection (2 papers, 2023). The state of being infected such as from the introduction of a foreign agent such as serum, vaccine, antigenic substance or organism. "Binding of STRN and STRN3 to the M1 protein was also observed by a complementary experimental approach using co-IP after infection of human 293T cells or murine MLE-15 cells with SC35M viruses." (PMID 36602306, 2023). "For the infection experiments, ACE2-A549 cells were depleted of STRN3 and PP2Aa for 48 hours prior to infection with the recombinant viruses expressing either NSP12P323 or NSP12L323." (PMID 37929963, 2023).
STRN3 also shares sentences with these, for which no sentence is quoted: autism (1 paper); hepatocellular carcinoma (1); myocardial infarction (1); pancreatic tumour (1); vitiligo (1).